NF1 (neurofibromin 1)
Diseases named in the same sentence as NF1 in open-access papers (continued):
Sharing a sentence is not in itself a finding about the gene and the disease.
cancer (continued). "The identification of structural rearrangement that disrupts the NF1 locus in subpopulation B illustrates that HiDENSEC can uncover novel large-scale chromosomal rearrangements and aneuploidies that drive cancer cell evolution, even when only present in small cancer cell populations." (PMID 37932252, 2023). "Moreover, NF1 appears amplified in almost 17% of a special type of breast cancer, i.e., adenoid cystic breast carcinoma, and in a significant minority of other specific cancers, including biliary tract, gastric, bladder urothelial, and pancreatic cancers." (PMID 37627552, 2023). "Despite there being evidence that synonymous mutations frequently contribute to human cancer, such studies have not been performed in NF1 yet, perhaps assuming that synonymous mutations may not alter neurofibromin function." (PMID 36009591, 2022). "Interestingly, Nichols and colleagues demonstrated that in several MAPK pathway mutant cancer-driven cancers, including non-V600E, class 3 BRAF mutant-driven cancers, NF1 deletion-driven cancers, and KRAS G12C mutant cancers, SHP2 inhibition is effective at inhibiting downstream MEK/ERK signaling." (PMID 35905710, 2022). "Neither NF1 nor other known cancer predisposition germline mutations were identified." (PMID 33580196, 2021). "Also, missense mutations that lead to NF1 disease and NF1-driven cancers occur throughout the protein and are not localized specifically to the GAP-related domain." (PMID 31836666, 2020). "Importantly, this novel working model suggests that identifying the cell types and signalling pathways that underlie the capacity of the microenvironment to suppress malignant progression could open the door to novel treatments for cancer beyond NF1." (PMID 32439933, 2020). "The discovery that cancer can escape the cytotoxic capacity of T cells through checkpoint strategies has great potential to revolutionise the field of cancer therapeutics but, despite the clinical success of immune checkpoint inhibitors, T cells have received little attention in the context of NF1." (PMID 32439933, 2020). "In addition, RAS proteins play a key role in many more cancers through indirect activation, for example, as a result of aberrant signalling by receptor tyrosine kinases (RTKs), or by inactivation of negative regulators such as the NF1 tumour suppressor gene." (PMID 31182717, 2019). "Moreover, we identified four novel candidate cancer-associated genes (CTCF, ARHGAP35, NF1, and KDR) which may be crucial in the carcinogenesis of EEC." (PMID 30886832, 2019). "Since NF1 patients have a 10% lifetime chance of being ultimately diagnosed with MPNST and the incidence of MPNST is very low in the general population, this leads to the general idea that NF1 patients, harboring an NF1+/− microenvironment, are more susceptible to this cancer development." (PMID 30479396, 2018). "Intriguingly, recent sequencing efforts revealed that the NF1 gene is frequently mutated in multiple malignant tumors not typically associated with NF1 patients, suggesting that NF1 heterozygosity is refractory to at least some cancer types." (PMID 30479396, 2018). "In conclusion, the use of commercial multi-gene panels to confirm syndromic associations with cancer is problematic and the results of these should not in particular be used to refute the far better evidence from cohort studies backed up by biology in NF1." (PMID 30510771, 2018). "In addition, non-genetic alternative mechanisms might be operational in human cancers promoted by GRB10 and NF1 co-loss." (PMID 26000738, 2015).
cancer (continued). "Several of these genes are known oncogenes and tumor suppressors including Nf1, Pten, Myc and Fli1, while many others have not been directly associated with cancer and could be potential targets for therapy." (PMID 24827933, 2014). "Inhibition of these pathways, together with inhibition of the LIMKs by T56-LIMKi or other inhibitors, may also synergistically reverse the malignant phenotype of neurofibromin-depleted cells, including NF1−/− schwannoma in neurofibromatosis, and of other cancer cells." (PMID 22776759, 2012). "The novel screening principle proposed and demonstrated in this work could hold immediate implications for patients with known cancer risks such as genetic predispositions (BRCA-1, Nf1 mutations) or patients with a history of cancer who are at high risk for recurrence." (PMID 21589655, 2011). "Due to the similarities between NF1- and Kras-driven cancers, including a hyperactive RAS signaling pathway and aberrant inflammatory signaling, we tested MSU-42011 in relevant preclinical models of NF1." (PMID 40563570, 2025). "Other known recurrent cancer genes with ≥10 occurrences include PLEC, PDGFRA, NF1, ARID1A, BCOR, and ACVR1." (PMID 41312385, 2025). "In contrast, mutations in three other genes of the KRAS pathway, BRAF, SOS1, and NF1, were significantly more common in CDX2-suppressed cancers." (PMID 39452477, 2024). "Our study thus reveals a role of TSs in regulating metastasis via non-cell-autonomous modulation of the immune compartment and provides proof-of-principle for ICB targeting LAG3 for patients with NF1-, TSC1- or TGF-β RII-inactivated cancers." (PMID 38997291, 2024). "Our study reveals a novel PDE4DIP-mediated PKCε/NF1/RAS signal transduction axis and highlights PDE4DIP as a promising therapeutic target for KRAS-mutant cancers." (PMID 37355626, 2023). "Therefore, further studies are needed in order to better clarify, and maybe selectively potentiate, the cytotoxic and antitumoral effects of ROS intervention as well as the protective role of antioxidant compounds in preventing and contrasting the development of NF1-related cancers." (PMID 37627552, 2023). "Our results indicated NOTCH1, NOTCH3, FLCN, SOD1, SOD2, NF1, and TLR4 as upregulated proteins in different cancer types highlighting their role in cancer progression." (PMID 35001007, 2022). "The genomic profiling of GC PNM also identified alterations in other cancer-related genes, including NOTCH1, NOTCH2, NF1, and STK11." (PMID 35515115, 2022). "The first approved drug for NF1‐related inoperable PN, selumetinib, a MEK inhibitor that has shown activity against several advanced cancers." (PMID 35506373, 2022). "CXCL12, the ligand of CXCR4, which is secreted from activated fibroblasts, was proven to stimulate cancer cell migration and promote cancer cell invasion through EMT transition, and is also elevated in CAF1 compared to NF1/NF2." (PMID 35853880, 2022). "This chromosomal region contains several genes connected to cancers including EME1, BRCA1, ERBB2, NF1, RAD51C, BRIP1, BIRC5 and PPM1D." (PMID 34885154, 2021). "(ii) NF1 and NOTCH1 neoantigens represent potential therapeutic targets for immunotherapy in hypermutated cancers." (PMID 34503126, 2021).
cancer (continued). "SHP2 inhibition can be efficacious in targeting for BRAF RAS-GTP cancers, inactivation of neurofibromin 1 (NF1), and RAS cancers in which an oscillation of RAS is seen." (PMID 34845311, 2021). "CYT-low COAD tumors contained significantly more cancer genes harbored within chromothriptic regions (TCF12, NF1, ERBB2, JUN, JAK1 and BCL10)." (PMID 34316699, 2021). "We found that these CLCLs exist even in pivotal cancer-related genes, such as the STK11, NF1, SMARCA4, and PTEN genes." (PMID 32887687, 2020). "CLCLs were found to occur even in key cancer genes, such as the STK11, NF1, SMARCA4, and PTEN genes." (PMID 32887687, 2020). "For six of these, the deletion peaks map to well-known tumor suppressor genes (CDKN2A, PTEN, RB1, MAP2K4, NF1, and SMAD4) that are frequently deleted in multiple cancer types." (PMID 31341961, 2019). "To assess the expression of NF1 in GBM subtypes, we analyzed The Cancer Genome Atlas (TCGA) database." (PMID 30967630, 2019). "To make sure that these tumors originated from Nf1−/− Schwann cells, we crossed the PLPCreERT2; Nf1f/f mice to ROSA-LacZ reporter mice and observed a specific signal from cancer cells upon X-Gal staining." (PMID 30479396, 2018). "Several well-known cancer driver genes, such as RB1, PTEN and NF1, were suggested to be the targets of the regions." (PMID 27230211, 2016). "Many of the known oncogenes, such as ERBB2, EGFR and CCND1, are frequently amplified and many of the known tumor suppressor genes (TSGs), such as CDKN2A, PTEN, NF1 and RB1, are frequently depleted in various types of cancers." (PMID 27230211, 2016). "In contrast to findings of other blood-based studies, we found at least four NSCLC-associated markers that were involved in Ras/MAP kinase and cell growth control pathways highly relevant to cancer: DUSP6, GRB2, MDM2, and NF1." (PMID 27418131, 2016). "The 7 CGC genes that were detected by SomInaClust only included well-known (germline) cancer genes such as BRCA1, MEN1 and NF1." (PMID 25903787, 2015). "This is especially in view of the fact that no copy number alterations involving SPP1 have previously been reported in a variety of cancers and tissue types (by reference to COSMIC and CONAN), including NF1 MPNSTs." (PMID 25884485, 2015). "Among them, the following well-known cancer genes were found: MET, CDK4, MDM4, EGFR and PIK3CA (amplifications), and CDKN2A, MLLT3, HRAS, CARS and NF1 (deletions)." (PMID 23408991, 2013). "Some of the most paradigmatic examples of cancer genes such as BRCA1, BRCA2, NF1, and ATM are included in these two sets." (PMID 24204383, 2013). "Eighteen patients died, 44.4% from the GIST, 11.2% from another NF1-related cancer (mainly nervous system tumors) and 33.3% without obvious relationship to NF1 or GIST." (PMID 40043354, 2025). "Although deguelins have previously been studied as potential cancer therapeutics, their effects in the context of NF1 had not been previously investigated." (PMID 41294711, 2025). "To explore potential involvements of NF and SPRED2 in the phenotypes of BC cells, we first analyzed the expression of NF1 and SPRED2 mRNA in 57 human BC cell lines representing different subtypes using raw read count data from the Cancer Cell Line Encyclopedia." (PMID 41155378, 2025). "None of the patients with HPGL-PCC, NF1, and CC who had WB-MRI screening were diagnosed with cancer." (PMID 40138602, 2025). "Unlike cancer, which often follows a more time-limited illness trajectory, children with NF1 + CI have a lifelong, progressive condition." (PMID 40471421, 2025).
cancer (continued). "We therefore hypothesized that, in the setting of NF1 MPNST, certain end motifs are enriched which could facilitate early cancer screening." (PMID 38293154, 2024). "Moreover, several confirmed gender-related carcinogenic genes exhibit completely different distributions in male and female cancer samples, such as PIK3CA, NF1, EIF1AY, IGF1R, NRAS, KDM5D, UTY, and PPP6C." (PMID 39541191, 2024). "In our study, we sought to identify NF1-HGG sensitivities against agents targeting downstream RAS effector pathways (MAPK and AKT pathways) in combination with a broad array of approved and investigational anti-cancer drugs." (PMID 36730269, 2023). "For NF1, clinical efficacy is observed at doses lower than the recommended adult cancer dose, which also do not completely abrogate ERK phosphorylation." (PMID 35178568, 2022). "However, experimentally supported targets are likely biased towards more intensively studied miRNAs (most often those with lower miR-numbers) and genes (e.g., cancer-related PTEN and NF1)." (PMID 35495153, 2022). "We hypothesize that our observed NRas-BRAF clusters and the NRas interactions with Grb2, NF1, and GPI in clusters could serve as novel targets for cancer therapy." (PMID 36304112, 2022). "Consistent with our observation that low NF1-expressing NBs are sensitive to SHP099, Nichols and colleagues demonstrated that a different SHP2 allosteric inhibitor, RMC-4550, disrupts RAS loading and MEK/ERK activatior in several NF1 mutant cancer cells." (PMID 35905710, 2022). "Two patients (1.7%) developed a second cancer; both were carriers of NF1, and none of them had received GHRT." (PMID 36612052, 2022). "Pathologists must be aware of the presence of NF1 because cancer should not be confused with rare intrathyroid neurofibroma." (PMID 34025587, 2021). "The NF1 p.T700I and NOTCH1 p.V2153M neoantigens may represent potential targets for immunotherapy in hypermutated cancer patients." (PMID 34503126, 2021). "Furthermore, CAFs (CAF1, CAF2) showed higher expression of specific markers including a-SMA, fibronectin, and P4HA1, compared with NFs (NF1, NF2) and cancer cells (DLD-1, HCT-116), indicating the successful establishment of CAFs." (PMID 34930899, 2021). "First, the role of NF1 mutants and genetic modifiers has not been well-studied in many other clinical features, such as skin-fold freckling or other kinds of cancers." (PMID 34566848, 2021). "EGFR is frequently over-activated in cancer and studies have shown that it is not expressed by normal Schwann cells but it is overexpressed in subpopulations of NF1 mutant Schwann cells." (PMID 32858845, 2020). "In this review, we mainly discuss the relationship between NF1 and cancer therapeutic resistance, especially resistance to TKIs; therefore, the relationship between NF1 and other protein molecules will not be restated." (PMID 33061844, 2020). "This work suggests that NF1 activity on KRAS G13D does not occur to a large extent, and that it is not occurring within cancer cells as no changes in KRAS-GTP were detected even at high levels of NF1 expression." (PMID 33153459, 2020). "A large-scale survey of cancer genomic and therapeutic databases has identified five candidate genes, namely PIK3CA, BRAF, NF1, NRAS, and PTEN, the targeting of which could be suitable for combination therapy with immunotherapy." (PMID 32483262, 2020).
cancer (continued). "Using DNA copy number data from 9,744 human cancer specimens, we demonstrate that linear deletion limitation exists and exposes deletion-limiting genes for seven known deletion targets (CDKN2A, RB1, PTEN, MAP2K4, NF1, SMAD4, and LINC00290)." (PMID 31341961, 2019). "Despite these findings, other studies on the possible role of NF1 in tumorigenesis have indicated that expression of NF1 can be considered a negative prognostic factor in several cancer types." (PMID 31803613, 2019). "Neurofibromatosis 1 (NF1 [MIM: 162200]) is the most common non-chromosomal disorder affecting development and predisposing to cancer (approx. 1:2000–3000 live births)." (PMID 31730495, 2019). "Other notable mutated cancer genes were BRCA2, NF1, and GATA3, each occurring once in non-overlapping tumors." (PMID 31618954, 2019). "Given our findings, it will be important to assess whether low expression of the 80 confirmed genes is correlated with poor patient survival in other cancers where RAS signaling is elevated, such as EGFR or RAS-GAP (NF1) tumors." (PMID 30325918, 2018). "To understand if NF1 shallow deletions correlate with deregulated RAS signaling, we employed expression signatures developed from KRAS-mutant cancers and performed a secondary WGCNA analysis and unsupervised clustering with 788 genes related to ER, RAS and KRAS signaling pathways." (PMID 30182054, 2018). "We further divided the 160 cancer tissues into high, low and negative NF1 protein expression groups and assessed the correlation between NF1 expression and clinicopathological characteristics." (PMID 29137312, 2017). "CovEx identified extra NCG cancer genes MECOM and NF1 and CGC cancer gene IKBKB." (PMID 28415609, 2017). "Combination Q in nano form with regular chemotherapeutic drugs like ADR and MTX in NF1 and NF2 respectively may overcome MDR—a daunting task in cancer treatment." (PMID 27196562, 2016). "After splitting up the tumors according to genotype cluster (i.e. cluster 1: SDHx- and VHL-related PCC/PGL; cluster 2: RET-, NF1-, and TMEM127-related tumors), malignant tumors (n = 24) clustered more often in genotype cluster 1 (P<0.0001), compared to benign tumors (n = 33)." (PMID 25794004, 2015). "This overview will focus on mainly the oncological aspects of NF1 aberrations, given the recent discovery of somatic NF1 aberrations in various cancers in individuals without germline NF1." (PMID 25026295, 2014). "The AXL receptor tyrosine kinase has been implicated in several kinds of cancers, but so far no studies have investigated the role of AXL in NF1 related tumorigenesis." (PMID 25551830, 2014). "Because some of the large intrathoracic malignant tumors cannot be removed completely due to adjacent critical vital organs, early detection of intrathoracic MPNST is very important for long-term survival of the patients with NF1." (PMID 24971186, 2014). "We first modeled SMN development after CI and found that in-field solid tumor development after CI was significantly increased in the Nf1 mutant background compared to wildtype, and that the tumor histologies closely reflected SMN histologies arising in cancer survivors." (PMID 23565507, 2013). "These endothelial cells promoted cancer cell proliferation by secreting platelet-derived growth factor subunit B (PDGFB), which was stimulated by cancer cell-secreted vascular endothelial growth factor (VEGF), fibroblast growth factor 12 (FGF12), pleiotrophin (PTN) and neurofibromin 1 (NF1)." (PMID 24977105, 2012). "Indeed, multiple upstream regulators of Ras activation such as SOS1, SOS2, PTPN11, and GAB1 exhibit significant negative correlations with NF1 in the Cancer Dependency Map, supporting the importance of these genes as functionally opposing NF1 function." (PMID 40587782, 2025).